SPATA4 (spermatogenesis associated 4)
Description:
May play a role in apoptosis regulation.
Synonyms: TSARG2; SPEF1B; FAP178; CFAP178
Tractability: No criterion of Open Targets' tractability assessment is met for any kind of drug.
Gene: Protein-coding gene on chromosome 4 (176,184,579 to 176,195,585, reverse strand). Ensembl gene ENSG00000150628.
Subcellular location: Nucleus
Subcellular location (Human Protein Atlas): Nucleoplasm; Cytosol; Vesicles
Gene Ontology:
Molecular function: protein binding; microtubule binding
Biological process: regulation of cytoskeleton organization
Cellular component: nucleoplasm; nucleus; axoneme; cytoplasm
Genetic constraint (gnomAD): Loss-of-function variants: 30 observed, 25.36 expected, observed/expected ratio (o/e) 1.18, 90% interval 0.88 to 1.6. The upper end of that interval is the gene's LOEUF score, 1.6, which puts it in group 6 of 6, group 1 being the genes least tolerant of losing a copy. Missense variants: 341 observed, 321.68 expected, observed/expected ratio (o/e) 1.06, 90% interval 0.97 to 1.16. Synonymous variants: 111 observed, 123.54 expected, observed/expected ratio (o/e) 0.9, 90% interval 0.77 to 1.05.
Homologues: Orthologues: chimpanzee SPATA4 (99% identical), macaque SPATA4 (92% identical), dog SPATA4 (77% identical), pig SPATA4 (76% identical), rabbit SPATA4 (76% identical), rat Spata4 (70% identical), guinea pig SPATA4 (70% identical), mouse Spata4 (69% identical), tropical clawed frog spata4 (38% identical), zebrafish spata4 (35% identical). Paralogues in human: SPEF1 (16% identical).
Diseases named in the same sentence as SPATA4 in open-access papers:
SPATA4 is named in the same sentence as 3 diseases in open-access papers, as found by Europe PMC text mining. Sharing a sentence is not in itself a finding about the gene and the disease. The quoted sentences say what the papers report.
cryptorchidism (3 papers, 2013 to 2021). The failure of one or both testes of a male fetus to descend from the abdomen into the scrotum during the late part of pregnancy. "Spermatogenesis associated 4 (Spata4) was initially identified in human testes and plays an important role in cryptorchidism development." (PMID 24146794, 2013).
SPATA4 also shares sentences with these, for which no sentence is quoted: breast carcinoma (1 paper); Infertility (1).